PPARG (peroxisome proliferator activated receptor gamma)
Description:
Ligand-activated transcription factor that forms obligate heterodimers with the retinoic acid receptor and acts as a key regulator of biological processes, such as adipocyte differentiation, lipid metabolism, glucose homeostasis and beta-oxidation of fatty acids. Activated by lipid ligands: binds peroxisome proliferators, such as hypolipidemic drugs, and fatty acids, such as prostaglandin J2 metabolites. Ligand-binding results in a conformational change in the receptor, promoting dissociation of repressors and recruitment of coactivators, and subsequent activation of target gene expression. Specifically binds to DNA specific PPAR response elements (PPRE) and modulates the transcription of its target genes, such as acyl-CoA oxidase (By similarity). Acts as a critical regulator of gut homeostasis by suppressing NF-kappa-B-mediated pro-inflammatory responses. Plays a role in the regulation of cardiovascular circadian rhythms by regulating the transcription of BMAL1 in the blood vessels (By similarity). [Isoform 2]: Nuclear receptor that acts as the key factor controlling the development of adipocytes (By similarity). Specifically activated by 15-deoxy-delta12,14-prostaglandin J2 ligand during early adipogenesis, driving differentiation of all types of adipocytes (white, beige and brown) (By similarity). Acts together with retinoic acid receptor RXRA, forming the ARF6 complex, which acts as a key regulator of the tissue-specific adipocyte P2 (aP2) enhancer (By similarity). Following recruitment of TLE3, promotes differentiation of white adipocytes (By similarity). Following recruitment of PRDM16, promotes differentiation of myoblastic precursors into brown adipose cells (BAT), which are specialized in dissipating energy in the form of heat in response to cold or excess feeding (By similarity). Also mediates diffentiation of white adipocytes into beige adipocytes by mediating recruitment of PRDM16 (By similarity). (Microbial infection) Upon treatment with M.tuberculosis or its lipoprotein LpqH, phosphorylation of MAPK p38 and IL-6 production are modulated, probably via this protein.
Synonyms: NR1C3; PPARG1; PPARG2; PPARgamma; CIMT1; FPLD3; GLM1; PPARG5
Tractability: Small molecule: an approved drug acts on it; a structure with a bound ligand is known; a high-quality ligand is known; it has a high-quality binding pocket; it belongs to a druggable protein family. PROTAC: UniProt records ubiquitination sites on it; ubiquitination databases record sites on it; a small molecule that binds it is known.
Target class: Nuclear hormone receptor subfamily 1; Nuclear hormone receptor subfamily 1 group C member 3; Transcription factor; Nuclear hormone receptor subfamily 1 group C; Nuclear receptor
Chemical probes: AD-5061, CHEMBL461571, GW1929 (high quality), PD080752, PD081087, PD081129, PD081203, PD081442, PD081607, PD081615, PD081668, PD081925, PD082371, PD082478, PD082498, PD082572, PD082624, PD082658, PD082698, PD082817, and 20 more
Safety:
Unwanted effects reported when the protein is acted on. In parentheses: how it was acted on, where the effect was seen, and who reports it.
decreased blood glucose (activation, acute dosing; renal, immune, cardiovascular; source: Lynch et al. (2017))
decreased inflammation (activation, acute dosing; renal, immune, cardiovascular; source: Lynch et al. (2017))
decreased platelet aggregation (activation, acute dosing; renal, immune, cardiovascular; source: Lynch et al. (2017))
decreased urinary sodium excretion (activation, acute dosing; renal, immune, cardiovascular; source: Lynch et al. (2017))
decreased urine excretion (activation, acute dosing; renal, immune, cardiovascular; source: Lynch et al. (2017))
heart failure (activation, acute dosing; renal, immune, cardiovascular; source: Lynch et al. (2017))
increased body weight (activation, acute dosing; renal, immune, cardiovascular; source: Lynch et al. (2017))
increased heart weight (activation, acute dosing; renal, immune, cardiovascular; source: Lynch et al. (2017))
increased inflammation (inhibition, acute dosing; renal, immune, cardiovascular; source: Lynch et al. (2017))
increased plasma volume (activation, acute dosing; renal, immune, cardiovascular; source: Lynch et al. (2017))
increased water retention (activation, acute dosing; renal, immune, cardiovascular; source: Lynch et al. (2017))
obesity (activation; source: AOP-Wiki)
Increased, Liver Steatosis (source: AOP-Wiki)
aspirin hypersensitivity (source: ClinPGx)
N/A, Liver Steatosis (source: AOP-Wiki)
weight gain (source: ClinPGx)
Gene: Protein-coding gene on chromosome 3 (12,287,368 to 12,434,574, forward strand). Ensembl gene ENSG00000132170.
Subcellular location: Nucleus; Cytoplasm; Nucleus (Isoform 2)
Subcellular location (Human Protein Atlas): Nucleoplasm; Vesicles
Pathways (Reactome):
Gene expression (Transcription): MLL4 and MLL3 complexes regulate expression of PPARG target genes in adipogenesis and hepatic steatosis; Nuclear Receptor transcription pathway
Developmental Biology: Transcriptional regulation of brown and beige adipocyte differentiation by EBF2; Transcriptional regulation of white adipocyte differentiation
Metabolism: PPARA activates gene expression
Metabolism of proteins: SUMOylation of intracellular receptors
Signal Transduction: Regulation of PTEN gene transcription
Gene Ontology:
Molecular function: alpha-actinin binding; DNA binding; DNA binding domain binding; DNA-binding transcription activator activity, RNA polymerase II-specific; DNA-binding transcription factor activity; DNA-binding transcription factor binding; double-stranded DNA binding; enzyme binding; identical protein binding; LBD domain binding; nuclear receptor activity; nuclear retinoid X receptor binding; nucleic acid binding; peptide binding; protein binding; R-SMAD binding; RNA polymerase II cis-regulatory region sequence-specific DNA binding; sequence-specific DNA binding; STAT family protein binding; transcription cis-regulatory region binding; transcription coregulator binding; WW domain binding; zinc ion binding; arachidonate binding; chromatin binding; and 4 more
Biological process: BMP signaling pathway; cell maturation; cellular response to insulin stimulus; cellular response to low-density lipoprotein particle stimulus; glucose homeostasis; monocyte differentiation; mRNA transcription by RNA polymerase II; negative regulation of angiogenesis; negative regulation of blood vessel endothelial cell migration; negative regulation of BMP signaling pathway; negative regulation of cellular response to transforming growth factor beta stimulus; negative regulation of cholesterol storage; negative regulation of extracellular matrix assembly; negative regulation of gene expression; negative regulation of macrophage derived foam cell differentiation; negative regulation of MAPK cascade; negative regulation of miRNA transcription; negative regulation of mitochondrial fission; negative regulation of osteoblast differentiation; negative regulation of receptor signaling pathway via STAT; negative regulation of SMAD protein signal transduction; negative regulation of smooth muscle cell proliferation; negative regulation of transcription by RNA polymerase II; negative regulation of transforming growth factor beta receptor signaling pathway; negative regulation of type II interferon-mediated signaling pathway; and 48 more
Cellular component: cytoplasm; nucleoplasm; nucleus; receptor complex; RNA polymerase II transcription regulator complex; chromatin; cytosol
Genetic constraint (gnomAD): Loss-of-function variants: 17 observed, 40.58 expected, observed/expected ratio (o/e) 0.42, 90% interval 0.29 to 0.63. The upper end of that interval is the gene's LOEUF score, 0.63, which puts it in group 2 of 6, group 1 being the genes least tolerant of losing a copy. Missense variants: 406 observed, 617.31 expected, observed/expected ratio (o/e) 0.66, 90% interval 0.61 to 0.71. Synonymous variants: 223 observed, 228.62 expected, observed/expected ratio (o/e) 0.98, 90% interval 0.87 to 1.09.
Gene-disease validity (ClinGen):
ClinGen rates the evidence that PPARG causes each of these diseases.
lipodystrophy (semidominant): Definitive. A congenital or acquired disorder characterized by abnormal loss or redistribution of the adipose tissue in the body.
Cancer hallmarks: proliferative signalling (promotes); change of cellular energetics (promotes); suppression of growth (promotes)
Homologues: Orthologues: chimpanzee PPARG (99% identical), macaque PPARG (99% identical), dog PPARG (99% identical), pig PPARG (99% identical), mouse Pparg (98% identical), rat Pparg (98% identical), rabbit PPARG (98% identical), guinea pig PPARG (96% identical), tropical clawed frog pparg (82% identical), Caenorhabditis elegans sex-1 (24% identical), Drosophila melanogaster EcR (21% identical), Caenorhabditis elegans nhr-114 (19% identical), and 182 more. Paralogues in human: PPARA (55% identical), PPARD (52% identical), NR1D2 (30% identical), NR1D1 (28% identical), RORA (25% identical), RARB (24% identical), RARA (24% identical), RARG (24% identical), RORC (24% identical), RORB (23% identical), THRB (23% identical), NR1H2 (22% identical), and 6 more.
Diseases named in the same sentence as PPARG in open-access papers:
PPARG is named in the same sentence as 813 diseases in open-access papers, as found by Europe PMC text mining. Sharing a sentence is not in itself a finding about the gene and the disease. The quoted sentences say what the papers report.
Obesity (1,512 papers, 2005 to 2026). Accumulation of substantial excess body fat. "While TGFB1 inhibits ASPC commitment to adipocytes, CDK5 has been associated with dysregulated PPARγ signaling in obesity." (PMID 40975767, 2025). "These factors, especially PPARγ, play a key role in adipocyte maturation and are associated with metabolic pathologies such as obesity and insulin resistance." (PMID 40332335, 2025). "While some studies suggest that adiponectin levels are negatively associated with obesity, others have reported an increased expression of adiponectin and PPARγ levels in adipocytes under certain conditions." (PMID 39858523, 2025). "They affect energy homeostasis by influencing nuclear receptors such as Erα, Erβ, PPARγ, TRs, and ARs, increasing the risk of obesity." (PMID 39775248, 2025). "Since RXRγ functions as a heterodimeric partner of PPARγ in adipose tissue, it is likely that these age/obesity-associated impairments in PPARγ would undermine RXRγ-PPARγ target gene activation, including UCP1." (PMID 40855678, 2025). "An illustration is that of mild obesity‐related diabetes (MORD): here, PPARγ variants lead to increased adipogenesis and obesity, contributing to IR." (PMID 40673471, 2025). "Key genetic variations, including SNPs in FTO (fat mass and obesity-associated) and PPARγ (peroxisome proliferator-activated receptor gamma), play significant roles in metabolic regulation, affecting insulin sensitivity, lipid metabolism, and energy balance." (PMID 40004938, 2025). "Our study highlights the intricate association between plasma FA profiles and PPARγ gene expression in adipose tissue, particularly in the context of obesity." (PMID 40968591, 2025). "Our results are consistent with prior observations that elevated PPARγ expression in adipose tissue is associated with obesity." (PMID 40968591, 2025). "miR-27a exacerbates obesity-associated inflammation and metabolic dysfunction by suppressing PPARγ, driving M1 polarization and NF-κB-mediated insulin resistance." (PMID 40777826, 2025). "These epigenetic changes can stably activate or silence key genes within the AMPK/mTOR and PPARγ/C/EBPα networks over the long term, thereby providing a molecular “memory” that influences susceptibility to obesity and metabolic diseases." (PMID 41488302, 2025). "Peroxisome proliferator-activated receptor gamma is a nuclear receptor that controls the transcription of numerous genes linked to diabetes and obesity." (PMID 39762333, 2025). "Fat mass and obesity-associated gene and peroxisome proliferator-activated receptor gamma (PPAR gamma) are examples of genes that affect metabolic regulation, involve the host genotype and interact with the GM." (PMID 41157183, 2025). "In this respect, it is well known that the decreased expression of peroxisome proliferator-activated receptor gamma (PPARγ) inhibits adipogenesis, compensated by AT hypertrophy in obesity, increases ectopic fat accumulation, and increases the risk of IR." (PMID 40871639, 2025). "Outdated, the pharmacological suppression of PPARγ has been used to manage obesity-associated complications." (PMID 41373668, 2025). "Sex-differential disease-related genes include those associated with obesity (PPARG, INSR), cancer (FGFR1, CD22), and immunity (IL6R, IL3RA)." (PMID 40707586, 2025). "Dysregulation of PPARG has the potential to cause obesity due to its important role in adipogenesis and adipocyte gene expression." (PMID 39208245, 2024). "A critical role of PPARγ in metabolic regulation has been implied from previous clinical studies showing the protective effects of human PPARγ gene polymorphisms on obesity and T2D." (PMID 39857594, 2024). "A missense mutation of PPARγ (rs1801282; C>G; Pro12Ala) plays an essential role in the pathogenesis of obesity." (PMID 38397196, 2024). "Many diseases had been linked to the dysregulation of PPARγ, such as obesity, type 2 diabetes and atherosclerosis." (PMID 38263024, 2024).
Obesity (continued). "Our results not only provide an advanced molecular insight into the structural ligand‐binding details in PPARγ, but also develop a linked selective and safe agonist for obesity treatment." (PMID 38988496, 2024). "We previously generated a Crtc1−/− mouse line using CRISPR/Cas9 and found that Crtc1 deficiency caused spontaneous obesity through regulating the PPARγ pathway." (PMID 38644501, 2024). "These exceptional features of PPARγ+ macrophages likely establish the mechanism underlying the pathogenesis of human metabolic dysfunction in obesity, which is associated with excessive IMAT accumulation." (PMID 39857594, 2024). "Other common polymorphisms of the PPARγ gene are rs3856806; C>T; His447His, which is involved in an increased risk of obesity, coronary heart disease, or colorectal cancer, and rs1800571; Pro115Gln." (PMID 38397196, 2024). "It has also been demonstrated to bind to PPARγ and reduce obesity-associated inflammation, as well as reduce pro-inflammatory cytokine production by inhibiting NF-κB and TNF-α activation in a carrageenan-induced inflammation murine model." (PMID 39458839, 2024). "This choice was based on their strong protein-protein interactions and GO analysis, which highlighted the involvement of AKT1 and PPARG, genes that have been extensively associated with obesity." (PMID 39409084, 2024). "Peroxisome proliferator-activated receptor gamma (PPARγ) plays a pivotal role in metabolic regulation and adipogenesis, making it a target of interest in understanding the development of obesity and associated health impacts." (PMID 38927044, 2024). "PPARγ regulates fatty acid storage and carbohydrate metabolism and has also been implicated in several diseases including obesity and diabetes." (PMID 39514580, 2024). "Some of them—like PPARγ mutation (rs1801282; C>G; Pro12Ala)—were described in elderly subjects to be a risk factor for increased obesity, especially in subjects with high carbohydrate intake with the co-presence of one rs9939609 allele of FTO gene." (PMID 38397196, 2024). "PPARγ agonists have shown to cause lipid accumulation and release of adipocyte-related hormones, resulting in an increased susceptibility to obesity." (PMID 38733764, 2024). "A number of prevalent metabolic disorders such as obesity, atherosclerosis and type 2 diabetes mellitus are associated with a shift in this balance, so PPARα and PPARγ in particular, are of interest pharmacologically." (PMID 39040675, 2024). "PPARγ deficiency triggers an exacerbation of age-associated obesity and metabolic failure in the subcutaneous adipose tissue of aged mice." (PMID 38874666, 2024). "Studies with PPARγ-gen knock-down animal models result in a protective effect on the development of diseases linked to overweight and obesity." (PMID 36986539, 2023). "This can be attributed to their anti-inflammatory properties and their ability to regulate genes associated with obesity, such as PPARγ and those within the ALOX family." (PMID 38024342, 2023). "Studies have identified leptin, aromatase, insulin receptor, peroxisome-proliferator-activated receptor gamma (PPARγ), and lifestyle changes as other potential targets for obesity-associated breast cancer treatment." (PMID 37626871, 2023). "The LPL and APIPOQ genes of this cluster are associated with obesity induced by the consumption of high-fat foods and show a strong association with the PPARG gene, which forms the second cluster." (PMID 36982283, 2023). "PPARγ is considered the master regulator of adipogenesis and its activation ameliorates the insulin resistance and inflammation associated with obesity." (PMID 37299580, 2023). "The adipocyte‐specific acetylation‐mimetic mutation of PPARγ K293Q (aKQ) restrains adipose plasticity during calorie restriction and diet‐induced obesity, associated with proteolysis of a core circadian component BMAL1." (PMID 36394167, 2023).